CXCL12 (C-X-C motif chemokine ligand 12)
Diseases named in the same sentence as CXCL12 in open-access papers (continued):
Sharing a sentence is not in itself a finding about the gene and the disease.
breast carcinoma (continued). "This study aims to verify the significance of CXCR4, CCR7 and their CXCL12 and CCL21 ligands, together with EGFR in the evaluation of metastasis and the prognosis of breast cancer." (PMID 20181250, 2010). "Reflecting our previous studies in breast cancer carcinomas, CXCR4 surface expression was unaltered between control and CXCL12-expressing cells." (PMID 20877573, 2010). "Through interaction with its cognate ligand, the chemokine stromal-derived factor-1 (SDF-1/CXCL12), CXCR4 is proposed to direct homing of breast cancer cells to particular sites of metastases." (PMID 21167057, 2010). "The CXCR4, CCR7, CXCL12, CCL21, and EGFR biomarkers were analyzed along with ER, PR, and HER-2/neu in breast cancer tissue microarray (TMA) specimens, including 200 primary breast cancer specimens by immunohistochemistry." (PMID 20181250, 2010). "Inaddition to mediating the directional homing of primary breast cancer cells tosecondary organ sites, CXCR4 and CXCL12 are important in other aspects ofcancer progression, such as adhesion, proliferation, and angiogenesis." (PMID 19325924, 2009). "Binding of CXCL12 to CXCR4 has been shown toincrease cellular secretion of VEGF in ovarian cancer, breast cancer,prostate cancer, and malignant glioma." (PMID 18779872, 2008). "For example, stromal cell-derived factor-1 (SDF-1/CXCL12) released from fibroblasts promotes cancer cell proliferation through a specific receptor, CXCR4, in several types of malignancies, including breast cancer and pancreatic cancer." (PMID 18594526, 2008). "The only known receptor for CXCL12, CXCR4, was previously shown to be expressed in different cancers including cutaneous melanoma, colon cancer, prostate cancer, breast cancer and neuroblastoma." (PMID 17261188, 2007). "The ligands for these receptors – CXCL12 (SDF-1) for CXCR4 and CCL21 for CCR7 – exhibit high expression in organs in which breast cancer metastases are often found." (PMID 15978137, 2005). "In addition, IL-24 can exert antitumor effects through CXCR4/CXCL12, and CXCL10, CXCL12 and CXCR4 are highly expressed in breast cancer tissues." (PMID 40076586, 2025). "Moreover, the CXCR4‒CXCL12 axis, along with phosphorylated mTOR, can induce the EMT program in metastatic breast cancer." (PMID 40740236, 2025). "For instance, in breast cancer, the chemokine receptor CXCR4 is overexpressed and its natural ligand, CXCL12, was shown to be highly secreted near the organs that are the metastatic destination of the tumor cells, indicative of a key role in metastatic colonization." (PMID 39698539, 2024). "Similarly, CAFs trigger monocyte recruitment and provoke differentiation of monocytes to M2 macrophages by secreting SDF-1 (CXCL12), monocyte chemotactic protein 1 (MCP1), and CHI3L1 in breast cancer." (PMID 38715072, 2024). "Moreover, Ahsg, in conjunction with the chemokine CXCL12 (also called stromal-derived factor-1 (SDF-1)), has been shown to enhance chemotaxis in in vitro studies of breast cancer cells." (PMID 39684629, 2024). "In bone metastases, osteoblasts in the bone marrow can attract CTCs using chemoattractants like ligand stromal cell-derived factor-1 (SDF-1) or C-X-C motif chemokine 12 (CXCL12), which binds to C-X-C motif receptor 4 (CXCR4) receptors highly expressed in breast cancer cells." (PMID 38231464, 2024). "In addition, CXCR7 on the surface of breast cancer cells reduced CXCR4 signaling by internalizing and degrading CXCL12." (PMID 37497001, 2023). "We found that high expression level of CXCL12 correlated with a better survival among luminal A/B and normal-like subtype breast cancer patients." (PMID 37564657, 2023). "CXCL12 stimulates the proliferation of CD44-positive and CD24-negative breast cancer stem cells." (PMID 37496657, 2023). "The NF-κB signaling pathway is downstream of the CXCL12/CXCR4 axis, and its activation contributes to cancer cell survival and invasion in various types of cancer, including prostate, pancreatic, lung, and breast cancer." (PMID 38004606, 2023).
breast carcinoma (continued). "Previous studies show that metformin downregulates the CXCL12/CXCR4 signaling in breast cancer and prostate cancer cell lines; nevertheless, no data were supporting this pleiotropic effect of metformin in the small intestine so far." (PMID 37795356, 2023). "We found out that the expression level of CXCL12 was lower in breast cancer tissues compared with that in normal breast tissues." (PMID 37564657, 2023). "Nevertheless, it is still not straightforward to delineate the complex role of CXCL12 and CXCL12-related biomarkers in the diagnosis and treatment of breast cancers." (PMID 37564657, 2023). "Furthermore, the stroma of human breast cancer presents less DPP4 expression than normal breast tissues, and the suppression of DPP4 promotes cancer metastasis via CXCL12 signaling." (PMID 35300413, 2022). "This means that 68Ga-Pentixafor could help guide therapy by identifying tumours that would respond to therapies targeting the CXCR4/CXCL12 axis; however it cannot replace 18F-FDG PET/CT in the staging of breast cancer." (PMID 36140541, 2022). "Additionally, the CAF-S1 FAP+ subpopulation is an important source of CXCL12 secretion, which plays a crucial role in resistance to anti-PD-1 and anti-CTLA-4 immunotherapies in pancreatic, ovarian, and breast cancer." (PMID 35745648, 2022). "Based on our results obtained using GEO disease data and molecular docking analysis, we suggest that the intervention of formononetin in breast cancer may be achieved by regulating IGF1, ESR1, and CXCL12." (PMID 35463082, 2022). "A large number of studies have proved that the combination of breast cancer cell CXCR4 and its ligand CXCL12 can promote the proliferation of primary tumor and distant metastasis of liver, lung, and brain, which will aggravate the patient's condition and increase the difficulty of treatment." (PMID 35979048, 2022). "By secreting CXCL12, CAFs attract conventional CD4+ T cell migration through its receptor-CXCR4 and promotes their differentiation into Foxp3+ regulatory T cells to create an immunosuppressive environment in human breast cancer." (PMID 35853880, 2022). "Thus, we tested the efficacy of combination treatment with a chemical inhibitor of S100A9 or CXCL12 and αPD1 in BRCA1-MT mice, and found the treatment significantly inhibited mammary tumor growth, recurrence, and metastasis." (PMID 35304461, 2022). "In addition to CXCR4, CXCL12 can also bind to CXCR7, a receptor that is overexpressed within the primary tumors vascular system and holds a more elaborate role in breast cancer progression." (PMID 34066014, 2021). "CXCL12 and TRAIL expressed in the MME of the boneregulate Akt signaling and survival responses in bone‐metastasizing breast cancer cells, and neutrophil‐derived leukotrienes supported the colonization of lung‐metastasizing breast cancer cells." (PMID 32761606, 2021). "Indeed, TCDD, the highly toxic AhR agonist, cannot be used in the clinic to specifically target AhR, despite its positive effect against breast cancer, by disrupting the CXCR4/CXCL12 pathway, or ovarian cancer cells." (PMID 33451095, 2021). "Recent mechanistic study has revealed that high POU1F1 expression in breast cancer patients is positively correlated with metastasis in liver and lung, and POU1F1/CXCL12/CXCR4 axis is involved in macrophage recruitment and polarization, as well as metastatic process." (PMID 33927188, 2021). "In contrast, knockout mice with selective depletion of CXCR7 in vascular ECs present more spontaneous lung metastases in “in vivo” breast cancer model, indicating that CXCR7 by sequestration of CXCL12 could limit cancer metastases development." (PMID 33937018, 2021). "Furthermore, cancer-associated fibroblasts drive the selection of bone-metastatic breast cancer cells by selecting highly CXCL12- and IGF-1-responsive cells with an Src-dependent sensitivity for CXCL12- and IGF-1-mediated AKT activation." (PMID 34064589, 2021).
breast carcinoma (continued). "Evidence revealed that the activation of CXCL12/CXCR4 could promote invasion and metastasis in breast cancer, gastric cancer 9 and glioblastoma." (PMID 34170080, 2021). "Dormant breast cancer cells reside in specific bone marrow niches that regulate their entry into the bone marrow via E-selectin, while anchoring them to the microenvironment via CXCR4/CXCL12 axis." (PMID 35006432, 2021). "Moreover, expression of CXCL12 and CXCR4 have been reported to have prognostic value for worse overall survival in breast cancer." (PMID 34359625, 2021). "CXCR4 is known to be hypomethylated and overexpressed, while CXCL12 is hypermethylated and absent in breast cancer cell lines and primary tumors themselves." (PMID 34901003, 2021). "In addition, CXCL12 inhibits DPP4 and accelerates EMT and metastasis in breast cancer, and the inhibition of ERBB3 signaling suppresses EMT of hepatocellular carcinoma." (PMID 33463049, 2021). "Histological evaluations showed that in MMTV-Wnt1 tumors high levels of epithelial or stromal CXCL12 is observed and therefore anti CXCL12 neutralizing abs effectively inhibited breast cancer derived from MMTV-Wnt1 but not Her2 induced breast cancer." (PMID 34445691, 2021). "Finally, we recommend further studies to determine the integrated effects of CXCL12, CXCR4, and CXCR7 on host immune responses to breast cancer." (PMID 35111484, 2021). "CXCL12 and its cell surface receptor CXCR4 combine to enhance the migration of breast cancer cells." (PMID 32847038, 2020). "CXCL12 (also known as stromal cell-derived factor 1 (SDF-1)) is expressed by a variety of cells of the bone microenvironment including osteoblasts and endothelial cells while cancer cells including breast cancer cells express CXCR4, the receptor for CXCL12." (PMID 32092997, 2020). "DPP-4, which cleaves CXCL12, prevents CXCL12induced EMT in breast cancer." (PMID 33096815, 2020). "Moreover, GLI1 also stimulates CXCL12-dependent ERK phosphorylation and migration of breast cancer cells." (PMID 33096815, 2020). "Also, the inactivation of CXCL12 stabilized endothelial tight junction expression like TJP-1 and occludin in breast cancer metastasis." (PMID 32210974, 2020). "Although CXCL12, CCL2, VEGF, MMP2, LOX, and CXCR4 were highly associated with HIF-1α expression, their prognostic significance in breast cancer is less so they were not chosen for further immunohistochemistry analyses." (PMID 33003428, 2020). "In breast cancer, ACKR3 has been shown to support scavenging of CXCL12." (PMID 33096815, 2020). "CXCL12/CXCR4 and CXCL16/CXCR6 chemokine signaling also mediates breast cancer progression." (PMID 32879136, 2020). "The dependence of myofibroblastic CAFs on autocrine TGF-β signaling remained unclear until a study demonstrated that the establishment of self-sustaining CXCL12 and TGF-β autocrine signaling pathways results in the formation of tumor-promoting CAFs during breast cancer progression." (PMID 32546182, 2020). "The CXCL12/CXCR4 signaling affects both innate and adaptive immunity in breast cancer." (PMID 33096815, 2020). "CXCL12 and RANKL, cytokines that are overexpressed by osteoblast-lineage cells and circulate in the blood, can attract CXCR4 and RANK, which are highly expressed on mammary tumor cells, inducing the latter to migrate to the bone surface." (PMID 32117996, 2020). "As zearalenone and apigenin activated ERs, we tested the potential effect of these molecules on the expression of endogenous E2-dependent genes, such as the chemokine CXCL12, the progesterone receptor (PgR), amphiregulin (AREG) and growth regulation in breast cancer 1 (GREB1)." (PMID 30678243, 2019). "CXCL12/CXCR4 axis in these cells mediates restrained cytotoxic T cell infiltration and builds up immunosuppressive tumor microenvironment in CT26, SL4 colorectal carcinoma, and E0771, MCa-M3C mammary carcinoma." (PMID 31474975, 2019).
breast carcinoma (continued). "Also in this case, a complex between AQP3 and Nox2 was found at the leading edge in polarized breast cancer cells, where a transient H2O2 accumulation occurred during CXCL12-induced chemotaxis." (PMID 30893772, 2019). "Experiments with breast cancer cell lines showed that inhibition of the chemokine receptor CXCR4 by a neutralizing antibody abrogates their metastasis to the lung, which expresses the corresponding chemokine ligand, CXCL12." (PMID 31477571, 2019). "Interestingly, significant positive correlation between CXCR7 and CXCL12 gene expression (Pearson = 0.3, p = 2.0 × 10–16) was observed in breast cancer patients, suggesting a biological role for the CXCR7/CXCL12 genetic circuit in breast cancer biology." (PMID 30993013, 2019). "Breast cancer cell studies showed that butein inhibits ER+ MCF-7 cells growth, and blocks CXCL12-induced migration and invasion of human epidermal growth factor receptor 2 positive (HER2+) in SKBR-3 breast cancer cells by repressing NFқB-dependent CXCR4 expression." (PMID 31665136, 2019). "The CXCL12/CXCR4 axis is strongly correlated with breast cancer aggressiveness and metastasis, whereas the CCL25/CCR9 axis provides chemotherapy resistance to breast cancer cells." (PMID 31616626, 2019). "So far, data regarding the involvement of the CXCR4/CXCL12 axis in FMC revealed that CXCR4 is overexpressed in the majority of FMC with frequent metastization at lymph node, liver and lung as reported in human breast cancer." (PMID 30012106, 2018). "Despite the fact that the spontaneous feline mammary carcinoma (FMC) is considered a suitable model for breast cancer studies, the importance of the CXCR4/CXCL12 axis in FMC is completely unknown." (PMID 30012106, 2018). "Furthermore, downregulation of CXCL12 expression by mesenchymal stromal cells in PT and upregulation of TGF-β and CXCR7, promotes breast cancer cell metastasis to the lungs." (PMID 30012106, 2018). "CXCL12 secreted by CAFs may also induce EMT, as has been reported for oral squamous cell carcinoma and breast cancer models." (PMID 29883428, 2018). "Several investigations report a role for the chemokine receptor CXCR4 and its ligand CXCL12 in site-specific metastasis, where neutralization of the CXCL12/CXCR4 interaction significantly impaired metastases formation in lymph nodes, bone, and lung in metastatic breast cancer models." (PMID 29037250, 2017). "Similarly, mouse breast cancer cell lines 410 and 410.4 migrated more across iSVEC4-10 than SVEC4-10 toward S1P or CXCL12." (PMID 28487567, 2017). "A recent study further supports a potential role of MMP2 in breast-to-brain metastasis, as it was found to belong to 5-gene expression signature (together with CXCL12, MMP11, VCAM1, MME) discriminating between primary breast cancer and breast cancer brain metastases." (PMID 29312881, 2017). "Moreover, binding of bone marrow-derived CXCL12 to its receptor CXCR4 can activate Akt, thus promoting breast cancer bone metastasis." (PMID 28356139, 2017). "We demonstrated that mouse and human breast carcinoma migration across LEC could be easily measured, responsive to different chemotactic signals (CXCL12, S1P), and display preference for the basal to apical direction as the leukocyte subsets." (PMID 28487567, 2017). "CXCR4 and its ligand CXCL12 (also named stromal cell-derived factor 1, SDF-1) have been shown to be consistently expressed in human breast cancer cells, and the activation of SDF-1α/CXCR4 axis has found to play a key role in breast cancer migration and metastasis." (PMID 28446538, 2017). "CXCL12 expression levels were undetectable in the parental line MDA-MB-231 (data not shown) and significantly lower in MDA-MB-231-B compared to the Luminal A (ER+, PR+/−, Her2−) MCF-7 breast cancer cell line." (PMID 26744352, 2016). "These evidences indicated a role of GLI1 in enhancing the CXCL12/CXCR4/CXCR7 signaling axis, which may be responsible for tissue-specific metastasis of breast cancer cells." (PMID 26413813, 2015).
breast carcinoma (continued). "Next, we shall clarify the role of CXCR7 in breast cancer growth and metastasis with or without CXCL12 stimulation." (PMID 26360780, 2015). "CAFs from invasive human breast carcinomas appear to control tumor cells by secreting a number of stromal cell-derived factors, the chief of which is stromal cell–derived factor 1 (SDF-1), also called CXCL12." (PMID 25774287, 2015). "CXCR4 may be overexpressed in breast cancer, and the CXCR4/CXCL12 axis is suggested to be involved in migration and consequently in the invasion and metastasis of breast cancer cells." (PMID 26576337, 2015). "Furthermore, we revealed that GLI1 up-regulated the expression of CXCR4, CXCR7, and LCP1 to enhance the CXCL12-induced ERK phosphorylation and migration of breast cancer cells." (PMID 26413813, 2015). "As self-renewal of human and animal mammary cancer stem cells involves a diverse network of regulatory mechanisms, including the signaling pathways of EGFR, CXCL12/CXCR4 and ER-alpha, we analysed whether these proteins are expressed in CMC cultures." (PMID 25884842, 2015). "The expression profiles of CXCL12, CXCR4 and CXCR7 in breast cancer biopsies are almost identical to that obtained when we overexpressed COUP-TFI in MCF-7 cancer cells, suggesting that our in-vitro results might have a clinical relevance." (PMID 24906407, 2014). "In addition, their respective ligands CXCL12 and CCL19/CCL21 exhibit peak levels of expression in organs representing the first destinations of breast cancer metastasis." (PMID 24915301, 2014). "In addition to CXCR4, breast cancer cells express another chemokine receptor, CXCR7, which binds to CXCL12 and introduces a new level of complexity in chemokine-receptor signaling." (PMID 24886617, 2014). "A number of functional studies investigating the influence of CXCR4 expression and activation by its ligand CXCL12 have recently been performed, revealing that CXCR4-CXCL12 axis plays an important role in regulating metastasis of breast cancer to specific organs." (PMID 24810923, 2014). "In addition to CXCR4, breast cancer cells express another chemokine receptor, CXCR7, which binds to CXCL12 with greater affinity than does CXCR4." (PMID 24886617, 2014). "In breast cancer, the activation of both CXCR4/CXCL12 and CCR7/CCL21 may reduce the sensitivity of metastatic cancer cells to anoikis by upregulating antiapoptotic proteins." (PMID 25110692, 2014). "As many proteins (such as MMPs, CXCL12 and VEGF) that are important in breast cancer are secreted, this could be highly significant." (PMID 24931391, 2014). "CAFs could promote breast cancer cell invasion under co-culture conditions through up-regulated CCL18 and CXCL12." (PMID 23577100, 2013). "Thus, we conclude that CB2-specific synthetic cannabinoids that do not possess psychoactivity can be developed to design novel therapies against breast cancer growth and metastasis by blocking CXCR4/CXCL12-induced signaling." (PMID 21915267, 2011). "When analyzing 100 breast cancer samples, IHC studies showed that groups highly expressing CXCL12 tended to be smaller tumors and lymph node negative (P = 0.04, P = 0.002)." (PMID 22295222, 2011). "However, it was barely detectable in the remaining cases (<10%), suggesting that CXCL12 expression might have been silenced, possibly through epigenetic mechanisms, such as promoter hypermethylation, a phenomenon already reported for colon carcinoma and breast cancer." (PMID 21410972, 2011). "Thus these results suggest that CB2 receptor specific agonists significantly reduced CXCL12/CXCR4-induced migration and invasion of breast cancer cells." (PMID 21915267, 2011). "Taken together, these observations indicate that enhancement of the expression of CXCL12 and CXCR4 by E2 may constitute a molecular mechanism by which breast cancer cells proliferate in response to that hormone." (PMID 21695171, 2011).